LINC01082 (long independently transcribed non-coding RNA 1082)
Synonyms: TCONS_00024492
Gene: Long non-coding RNA gene on chromosome 16 (86,151,351 to 86,244,348, forward strand). Ensembl gene ENSG00000269186.
Diseases named in the same sentence as LINC01082 in open-access papers:
LINC01082 is named in the same sentence as 7 diseases in open-access papers, as found by Europe PMC text mining. Sharing a sentence is not in itself a finding about the gene and the disease. The quoted sentences say what the papers report.
colon cancer (2 papers, 2020 to 2022). "LINC01082 is downregulated in colon cancer tissues, and LINC01082 upregulation inhibits cell proliferation in SW480 and SW620 colon cancer cells." (PMID 33246471, 2020). "LINC01082 expression is significantly downregulated in colon cancer tissues, and overexpression of LINC01082 can significantly suppress the proliferation of the colon cancer cells." (PMID 35144613, 2022). "Upregulation of LINC01082 inhibits the migration and invasion of SW480 and SW620 colon cancer cells, indicating that LINC01082 has antitumor activity in colon cancer." (PMID 33246471, 2020).
colon adenocarcinoma (1 paper, 2022). "LINC01082 has been found with the potential to predict the prognosis of urothelial bladder carcinoma and colon adenocarcinoma." (PMID 35075375, 2022).
osteosarcoma (1 paper, 2025). A usually aggressive malignant bone-forming mesenchymal neoplasm, predominantly affecting adolescents and young adults. "NSUN2-mediated m5C modification stabilizes LINC01082 through interaction with the m5C reader protein YBX1, increasing LINC01082 expression, which results in reduced proliferation and migration, as well as increased apoptosis of osteosarcoma (OS) cells." (PMID 41413017, 2025).
prostate carcinoma (1 paper, 2022). A carcinoma that arises from epithelial cells of the prostate gland. "We constructed ceRNA networks in the prostate cancer microenvironment and identified lncRNA LINC01082, miRNA hsa-miR-133a-3p, and genes TTLL12, PTGDS, GAS6, CYP27A1, PKP3, and ZG16B as the potential biomarkers to predict prognosis for prostate cancer." (PMID 35075375, 2022).
cancer (2 papers, 2017 to 2022). A tumor composed of atypical neoplastic, often pleomorphic cells that invade other tissues. "Based on TCGA data, we found that LINC01082 was significantly downregulated in cancer tissues." (PMID 35144613, 2022). "Finally, further functional study is recommended to elaborate the exact and distinctive roles of LINC00152 and LINC01082 that could pave the way for better understanding of cancer biology in terms of its development and treatment." (PMID 29988223, 2017).
tumor (2 papers, 2017 to 2021). "Downregulation of LINC01082 expression was also observed (P<0.001) in 90% of cases that was associated with tumor type (P= 0.05)." (PMID 29988223, 2017). "LINC01605, SNHG20, LUCAT1, and ZNF337-AS1 had significantly high expression in tumor tissues, while MEG9, LINC01082, and DICER1-AS1 had high expression in ADJ tissues." (PMID 34544413, 2021).
LINC01082 also shares sentences with these, for which no sentence is quoted: urothelial bladder carcinoma (1 paper).